NGF (nerve growth factor)
Diseases named in the same sentence as NGF in open-access papers (continued):
Sharing a sentence is not in itself a finding about the gene and the disease.
cancer (continued). "In the present study, we investigated the role of cancer cells in the autophagy of SCs by upregulating ATG7 expression, which is mediated by neurotrophic factors, such as NGF, secreted by cancer cells." (PMID 35109895, 2022). "Taken together, these results suggested that SorCS3 can weaken the cancer-promoting effect of NGF and that NGF can enhance the SorCS3-regulated internalization of p75NTR." (PMID 35393432, 2022). "To further verify that the biological function of SorCS3 in suppressing cancer is achieved through the NGF/p75NTR signalling pathway, we selected the competitive NGF inhibitor Ro 08-2750 to inhibit binding between endogenous NGF and p75NTR." (PMID 35393432, 2022). "Although the anatomical distribution within cancer cells is still unclear, the expression of NGF and TrkA are high in NSCLC." (PMID 36289793, 2022). "On the contrary, in breast cancer, NGF/TrkA signaling contributes to cancer progression via the activation of ERK, SRC, and AKT pathways similar to gastric and pancreatic cancer." (PMID 36289793, 2022). "To confirm that the combination of an NGF inhibitor and chloroquine exerts antipancreatic cancer activity and PNI in vivo, we next examined its efficacy in PANC-1 and BxPC-3 sciatic nerve PNI models." (PMID 35109895, 2022). "As NGF is one of the key players in cancer–nerve crosstalk, the link between retinoic acid and NFG in cancer of the nervous system calls for future studies to determine the full extent of this relationship." (PMID 35565690, 2022). "Due to its involvement in several biological processes, NGF-TrkA interaction represents an attractive target for pharmacological intervention in the therapy of AD, ocular dysfunctions, pain and cancer." (PMID 36139382, 2022). "NGF and TrkA are its high affinity receptors that play a crucial role in cancer pathogenesis through cell proliferation, angiogenesis, invasion, and migration." (PMID 36285300, 2022). "Previous studies have shown that NGF ameliorates the inhibitory effect of the neurotrophin (NTR) receptor on cell-cycle protein expression in cancer cells of BLCA." (PMID 35251120, 2022). "NGF is a neurotrophic factor which was the first growth factor discovered in cancer biology by Levi-Montalcini in the 1940s, as a substance secreted by a mouse sarcoma in 3-day-old chick embryos, that stimulated neurite outgrowth and neural survival." (PMID 35681586, 2022). "Cancer cells secrete NGF through paracrine pathways to promote neuroplasticity, thereby recruiting nerves and facilitating cancer cell invasion of nerves." (PMID 35449152, 2022). "At 48 h and 72 h, NGF was also detected in the culture medium of all five cancer cell lines at levels comparable to those at 24 h." (PMID 35109895, 2022). "Taken together, these data suggest that NGF and its receptors can cause PNI and make the TME favorable to cancer progression and metastasis." (PMID 34707166, 2021). "Cancer- or TNFα-activated Schwann cells release pro-nociceptive mediators such as TNFα and nerve growth factor (NGF)." (PMID 33469141, 2021). "NGF is able to act on immune cell activities and this enables NGF to play an important role in the immunity against cancer." (PMID 33288884, 2021). "PC12 is a cancer cell line derived from the rat adrenal glands, which, after incubation with nerve growth factor (NGF), differentiates into cells that resemble biochemically and phenotypically sympathetic nerves." (PMID 33188619, 2021). "The last years have seen intense investigations on the role of NGF and its receptors in human cancers." (PMID 34268306, 2021). "Small molecule inhibitors of TRKA and antibodies targeting NGF have been used in animal experiments and clinical trials to relieve cancer-associated pain, reverse PNI, and inhibit cancer growth." (PMID 33466373, 2021). "Several studies have demonstrated that the p75NTR low-affinity receptor of Nerve Growth Factor (NGF), is produced in abnormally large amounts in several human cancer types." (PMID 34209730, 2021).
cancer (continued). "In cancer cells, NGF was present as intense staining of cytoplasm and nuclei, while TrkA was found diffusely in the cytoplasm and along the surface membrane." (PMID 34885121, 2021). "On the other hand, nerve growth factor (NGF) is considered to be an inducer of cancer proliferation and its inhibition can be correlated with apoptosis induction." (PMID 34943856, 2021). "Precursor of nerve growth factor (proNGF) is a new and potential therapeutic target in cancer therapy." (PMID 34943856, 2021). "Multiple factors, such as endothelin, nerve growth factor (NGF), adenosine triphosphate, proton, and proteases, are released from cancer cells and attract immune cells to eventually induce the peripheral sensitization of nociceptive afferents." (PMID 34071720, 2021). "NGF treatment can trigger the cancer cells to stay in a more differentiated cell phenotype and thus reduce tumor growth." (PMID 33288884, 2021). "The binding of NGF with the neurotrophin receptor TrkA mediates the NGF control in the development of cancer." (PMID 34283074, 2021). "Therapies which target PNI are described in different cancer types, which mostly target NGF–TRKA signaling, because NGF is commonly overexpressed by cancer cells." (PMID 33466373, 2021). "Anti-NGF antibodies have been shown to be effective in preventing neurite growth into tumors in mice and in mitigating cancer-induced pain in humans." (PMID 33322770, 2020). "Cancer cells secrete factors such as NGF, ARTN, CXCL12/SDF-1 which attract Schwann cells, and Schwann cells secrete GDNF, TGF-β and provide NCAM-1-mediated cell-cell interaction to promote cancer cell migration and aggressiveness." (PMID 33050151, 2020). "Upregulation of the NGF precursor (proNGF) and an NGF-induced increase in nerve density have been reported in prostate and gastric cancer cells." (PMID 33322770, 2020). "NGF and its receptors (P75 and TrkA) were always shown to be the acceleration role for the cancer development." (PMID 32294802, 2020). "Drugs acting on the NGF-TrkA pathway have recently started to be clinically applied in the treatment of pain and cancer." (PMID 33037246, 2020). "The efficacy of blocking antibodies against NGF (e.g., tanezumab, fasinumab) in patients with pain or cancer-induced pain have been investigated in some clinical trials (NCT00830180)." (PMID 33392191, 2020). "Phosphoinositide 3‐kinase (PI3K)/protein kinase B(AKT) signalling pathway, which is the downstream of NGF/TrkA, promotes cancer survival and proliferation." (PMID 32294802, 2020). "This sprouting process was shown to be mediated via tyrosine kinase A (TrkA) receptor activation by nerve growth factor (NGF) released from both cancer and stromal cells." (PMID 33172040, 2020). "This opens the gates for screening NGF-BDNF-TRK pathways in cancer patients, and the modulation on IMT is a novel opportunity to augment the effect of anti-PD1 or anti-PD-L1 antibodies." (PMID 32516941, 2020). "Among the differentially expressed IRGs, we identified 5 IRGs (CD1B, XCL1, PLCG2, NGF, and OXTR) for inclusion in the risk score, and previous studies have indicated that these genes were related to immune processes and cancer progression." (PMID 32508884, 2020). "Here, we described for the first time, the relationship between NGF/TRKA and miR-145 in the context of cancer, contributing to clarify an additional pro-tumoral mechanisms of NGF/TRKA in EOC cells, which involves miR-145 regulation." (PMID 33081171, 2020). "Future clinical trials testing the antitumor efficacy of anti-NGF therapies will be necessary to understand their role in treating human cancers." (PMID 33322770, 2020). "Nerve growth factor (NGF) has been considered the most potent pain inducer across multiple cancer models and currently holds the most promise for management of pain associated with cancer initiation and progression." (PMID 33381048, 2020).
cancer (continued). "It is reported that the NGF signaling pathway is associated with TrKA or P75 NTR and cancer pain by triggering neurogenic inflammation." (PMID 32443847, 2020). "In recent years, studies had shown that NGF signaling alters cell death and survival in various cancer cells." (PMID 31839752, 2019). "Nerve growth factor (NGF) released by cancer can sensitize sensory nerves and act on TRPV1 (Transient Receptor Potential Vanilloid 1), which in turn correlates with severe pain in patients." (PMID 31248001, 2019). "NGF increase at the sites of inflammation and in systemic circulation is a common event in different inflammatory and autoimmune diseases, and in cancer." (PMID 31812953, 2019). "The ACh released from the Tuft cells promotes NGF upregulation within cancer cells expressing the ACh receptor, M3R." (PMID 30741921, 2019). "NGF stimulation of insulin pathway via IRS1 transactivation has been previously reported in cancer cells, and occurs upon IRS1 recruitment by the NGF receptor TrkA." (PMID 29736736, 2019). "This ability was found to be instrumental to reduce the cancer promoting ability of nerve growth factor (NGF) on HepG2 cells." (PMID 31766676, 2019). "Acetylcholine (Ach) is one of the most important neurotransmitters targeted by cancer pharmacotherapy and its metabolism is dependent upon NGF supply." (PMID 31812953, 2019). "On the other hand, an active NGF pathway has been recently proven to be critical to oncogenic inflammation control and in promoting immune response against cancer, pinpointing possible pro-tumoral effects of NGF/TrkA-inhibitory therapy." (PMID 31812953, 2019). "The other pathways are associated with cell cycle, development, immune response, and other cancer- related pathways (B-Raf, NGF, mTOR/MAPK and WNT signaling)." (PMID 31216276, 2019). "For example, it has been shown that NGF inhibition reduces cancer progression, similarly blocking NT–3–TrkC signaling slows PDAC growth in murine models." (PMID 31248001, 2019). "NGF released by cancer cells in the TME stimulates nerve fibers surrounding the niche containing the stem cells and stimulates them through the Trk receptor that they express, thus promoting an abnormal innervation from the bottom to the top of the epithelium." (PMID 30741921, 2019). "NGF is primarily involved in nerve growth and invasion of cancer cells by nerves, especially in GC through cholinergic signaling and in PDAC through adrenergic signaling." (PMID 30741921, 2019). "Taken together, the experimental findings here reported suggest opposite pro-oncogenic and anti-oncogenic actions of the NGF signaling pathway in the control of CSCs growth and cancer evasion from the host immune system." (PMID 31812953, 2019). "PNI is influenced by the interaction between the nerve microenvironment and neurotrophic molecules expressed by cancer cells such as nerve growth factor (NGF), BDNF, glial cell line-derived neurotrophic factor (GDNF) and their receptors." (PMID 29334991, 2018). "Similar to axon-guidance molecules, components of the neurotrophin/NGF signaling are beginning to unveil their importance in human cancer." (PMID 29459716, 2018). "NGF immunoreactivity was observed at low levels in normal tissues, and was increased in cancer vs normal samples." (PMID 29802376, 2018). "NGF staining intensity (h-score) was significantly increased from 57 in normal to 95 in cancer samples (p < 0.0001)." (PMID 29802376, 2018). "We experimentally excluded NGF and focused on EphrinB1 as its increased expression leads to aggressive disease in different human cancers as well as in the mEERL mouse model." (PMID 30327461, 2018). "This highlights the opportunity for gaining a better understanding of the impact of major lipid raft components on NGF receptor trafficking and subsequent NGF signaling in the context of cancer and neuronal differentiation." (PMID 28338624, 2017).
cancer (continued). "A previous study showed that nerve growth factor (NGF) family members such as NGF, neurotrophin-3, and neurotrophin-4/5, which are other ligands of TrkB, influence cancer proliferation." (PMID 28423707, 2017). "NGF is a key candidate in the pathological growth and aberrant sprouting of neurons in cancer, and has been shown to be responsible for increased pain in cancer." (PMID 29100335, 2017). "Regarding the role of the NGF signaling pathway in tumorigenesis, an association between the expression of NGFR TrkA and p75NTR has been reported in various types of cancers." (PMID 28679437, 2017). "The effects of NGF/tropomyosin receptor kinase A (TrkA) in cancer appear to be related to the cell type." (PMID 28557340, 2017). "NGF and proNGF are expressed by cancer cells and mediate cancer-related phenomena, such as angiogenesis and pain." (PMID 28282920, 2017). "NGF, through TRKA activation, can alter the expression of several molecules associated with cancer development and progression." (PMID 28245631, 2017). "This trend was previously observed in other types of human cancer cells when NGF significantly enhanced their proliferation and clonal growth." (PMID 28557340, 2017). "The nerve growth factor (NGF) is the first neurotrophic factor attributed to non‐neural functions including cancer cell survival, proliferation, and metastasis." (PMID 28557340, 2017). "Nerve growth factor (NGF) and its high affinity receptor tyrosine kinase A receptor (TRKA) have been associated with the development of several types of cancer, including EOC; both NGF and TRKA levels are elevated in this pathology." (PMID 28245631, 2017). "In the case of NGF signaling pathway, it has been shown to alter cell death and survival in various cancer cells." (PMID 29020948, 2017). "NGF and proNGF also mediate cancer pain through activation of TrkA on sensory neurons, and this pain can be ameliorated using TrkA inhibitors." (PMID 28282920, 2017). "Combined administration of ketoprofen and NGF to inoculated mice resulted in the outgrowth of connective tissue between carcinoma cells." (PMID 28878143, 2017). "The precursor for nerve growth factor (proNGF) is expressed in some cancers but its clinicopathological significance is unclear." (PMID 27074571, 2016). "On the contrary, NGF by itself is unable to induce/generate cancer cell proliferation from normal tissues/cells or sustain cancer cell progression." (PMID 27439311, 2016). "During recent years, a growing body of evidence supports a role for NGF/NGFRs signaling in tumorigenesis and progression which can urged cancer cells to override normal cell growth regulatory mechanisms." (PMID 27835587, 2016). "Up to now, however, there is little literature to examine their interaction and the resulting intracellular signaling between NGF/NGFRs and β-catenin in human cancers." (PMID 27835587, 2016). "We observed that p75 and trk family receptor mediated events, i.e. signalling by NGF, have genes with very high potential to cross-talk with other cancer related events." (PMID 26558755, 2015). "Nerve growth factor (NGF), the first growth factor discovered by Stanley Cohen and Rita Levi Montalcini, functions in both normal tissues and cancers of different origins." (PMID 25840418, 2015). "There is accumulating evidence that TrkA and its ligand Nerve Growth Factor (NGF) are involved in cancer development." (PMID 25840418, 2015). "Altogether, these results indicate that NGF induces association between TrkA and CD44 at the plasma membrane in cancer cells of various origins." (PMID 25840418, 2015). "In this report, we show that the NGF/TrkA axis engages CD44 as a co-receptor to strengthen cancer cell invasion and growth." (PMID 25840418, 2015). "Nerve growth factor (NGF), another cancer-derived pain mediator found in both human and mouse HNSCC, induces P2X2 and P2X3 hypersensitivity and increases subunit expression in murine trigeminal ganglion (TG) neurons." (PMID 24903857, 2014).
cancer (continued). "NTRK1 is a mediator of the pro-survival signaling of nerve growth factor (NGF) and is a known oncogene, found commonly altered in human cancer." (PMID 24647444, 2014). "Former studies also showed that analgesia produced by EA with low frequency was accompanied by inhibition of TRPV1 up-regulation in sensory neurons in diabetic neuropathic pain, nerve growth factor-induced hyperalgisea, and cancer-induced pain." (PMID 23935654, 2013). "Neutralising antibodies to NGF are highly effective analgesics in rodent models of inflammatory pain, arthritis pain, cancer pain, and bone fracture pain." (PMID 24206926, 2013). "In BRCA, NGF is shown to act as a mitogen for cancer cells through phosphorylation of TrkA, and it promotes survival and proliferation of cancer cells." (PMID 24180625, 2013). "Heparanase expression can be up-regulated by nerve growth factor (NGF) and NGF expression in astrocytes has been shown to be stimulated in response to cancer cell-secreted factors TGF-β1, IL-1β, and bFGF." (PMID 24213237, 2012). "In these cancers, NGF and other neurotrophins regulate cell proliferation and invasion as well as cell death and survival." (PMID 24212627, 2011). "Rapid advances in drug design, particularly rational design, make it likely that other approaches will be used to interfere with aberrant NGF/TrkA/p75NTR signaling in cancers." (PMID 24212627, 2011). "This review focuses on our current knowledge of neurotrophin signaling in cancer, with a particular emphasis on nerve growth factor regulation of cell death and survival in cancer." (PMID 24212627, 2011). "Here we discuss evidence regarding the role of nerve growth factor (NGF), the first growth factor discovered, in cancer biology with particular focus on its role in the death and survival of cancer cells." (PMID 24212627, 2011). "NGF is one such protein and during recent years, NGF signaling has been shown to alter cell death and survival in various cancer cells." (PMID 24212627, 2011). "Nerve growth factor (NGF) is overexpressed not only in nervous system, but also in several types of cancers." (PMID 16832412, 2006). "In addition, cancer cells respond dynamically to elevated ECM stiffness by upregulating NGF expression, facilitating interactions between cancer cells and nerve structures, and ultimately promoting PNI." (PMID 41556039, 2026). "In a phase 3 clinical trial, the NGF‐targeting monoclonal antibody, tanezumab, demonstrated significant analgesic efficacy for bone metastasis‐related pain, indicating its potential as a novel therapeutic option for cancer pain management." (PMID 41556039, 2026). "Blocking the NGF/TrkA pathway attenuates the development of cancer-induced bone pain." (PMID 39940997, 2025). "Further research into NGF/TrkA signaling and the effects of larotrectinib could advance therapeutic options for this aggressive cancer." (PMID 39860039, 2025). "NGF is essential for nociceptive sensory neurons, and its dysregulation has been linked to chronic pain, inflammation, certain neurodegenerative diseases, tumorigenesis, and cancer pain, making it a target for novel analgesics aimed at disrupting human NGF (hNGF) signalling pathways." (PMID 40733301, 2025). "Furthermore, signaling pathways crucial for PNI, like NGF/TrkA, can directly impact cancer cell metabolism by upregulating glucose transporters like GLUT1, further enhancing glycolytic flux." (PMID 40909268, 2025). "Pan-Trk inhibitors like Larotrectinib are approved for rare TRK fusion-positive cancers, but preclinical studies using specific TrkA inhibitors or NGF-neutralizing antibodies have shown they can reduce the PNI potential of PDAC cells and inhibit neurite outgrowth." (PMID 40909268, 2025). "Furthermore, nerve growth factor (NGF) regulation is controlled by acetylcholine, and the higher the NGF levels, the higher the possibility of cancer growth." (PMID 40143145, 2025).